MEN1 (menin 1)
Diseases named in the same sentence as MEN1 in open-access papers (continued):
Sharing a sentence is not in itself a finding about the gene and the disease.
insulinomas (continued). "Germline loss-of-function MEN-1 mutation leads to the formation of numerous microadenomas, mostly resulting in non-functional PNET and insulinomas, while MEN-1 associated gastrinomas are regularly located within the duodenum." (PMID 24281208, 2010). "It is important to note, especially in the context of MEN1, that 68Ga-DOTA-based PET/CT has low sensitivity for localized insulinomas, and in MEN1, where multiple pancreatic lesions are typical, it may identify a non-functioning PNEN rather than the insulinoma." (PMID 39826015, 2025). "In addition, the incidence of PHPT was only 78.2%, which is difficult to compare because of the lack of data related to MEN1 patients with insulinoma from other centers, and 32.7% of affected patients were symptomatic." (PMID 35698198, 2022). "Genetic cell lineage tracing revealed the α-cell lacking Men1 can transdifferentiate into insulinomas, suggesting Men1 could be a regulator of α-cell plasticity." (PMID 34680266, 2021). "However, studies of an α-cell specific Men1 knockout mouse model produced on a mixed genetic background that included the C57BL/6 mouse strain have reported that mice developed both glucagonomas and insulinomas." (PMID 32348957, 2020). "Moreover, this is also the first description of a synchronous nonfunctional tumor and insulinoma in a pediatric MEN1 patient." (PMID 28663159, 2017). "Finally, it remains to be determined, if the spectrum of the human MEN1-syndrome can be fully recapitulated in mice, since glucagon cell specific deletion of MEN1 in mice resulted in the development of insulinomas and not glucagon producing cells." (PMID 27769070, 2016). "MEN1 tumors (e.g., parathyroids, insulinoma, and lipoma) that do not have LOH have been shown to harbor different somatic and germ-line mutations of the MEN1 gene, and this is consistent with the Knudson two-hit hypothesis." (PMID 23933118, 2014). "While indications for localization and treatment of sporadic insulinoma are well established, clear guidelines could not be drawn for the management of MEN1 insulinoma." (PMID 24213321, 2012). "However, to our knowledge, no case series or epidemiological studies have described the characteristics of insulinomas in patients with MEN1 in the Chinese population and the effect of elevated serum Ca caused by PHPT on patients with insulinoma has not been studied." (PMID 35698198, 2022). "In addition, the prognosis of the subgroups of patients with metastatic, recurrent, or MEN1-related insulinomas could not be evaluated comprehensively." (PMID 34374651, 2021). "The most frequent functioning PanNETs in MEN1 and TSC are insulinomas, while in VHL, PanNETs are almost exclusively nonfunctioning." (PMID 38893191, 2024). "In contrast to normal feline β cells, insulinoma cells express the HK1 gene and do not show glucagon protein expression, similar to lacking glucagon protein expression within Men1-ablated murine insulinomas." (PMID 35769100, 2022). "In our studied samples of micro-tumors, we have not found alteration in MEN1, but gain status in IRS2, FOXL2 and CEBPA genes was found, suggesting that they can play a role in the development of micro- to macro-tumors, to wit insulinomas, and, accordingly, insulinomatosis." (PMID 34737724, 2021).
pituitary adenomas (95 papers, 2009 to 2026). "Genetic testing for MEN1 or AIP mutations should be considered in young patients with aggressive pituitary adenomas." (PMID 40599499, 2025). "It is an autosomal dominant disorder caused by mutations in the MEN1 gene, typically characterized by combined occurrence of parathyroid tumors, pancreaticoduodenal neuroendocrine tumors, and pituitary adenomas." (PMID 41272807, 2025). "Pituitary adenomas, one of the hallmark tumors of MEN1, arise from the anterior pituitary gland and are usually benign." (PMID 41155355, 2025). "Classically, MEN1 is associated with primary hyperparathyroidism, which occurs in over 90% of cases, pituitary adenomas, and neuroendocrine tumors of the gastrointestinal tract, particularly in the pancreas." (PMID 41155355, 2025). "Among the various neoplastic manifestations of MEN1, pituitary adenomas (PAs) are considered a classic diagnostic criterion and one of the three defining lesions of the disease." (PMID 39439563, 2024). "In comparison with patients with AIP/MEN1 mutations, the mean age of occurrence of pituitary adenomas is older: 42.4 years, ranging from 16 to 72 years." (PMID 39194755, 2024). "A case report recently published also describes a young individual with the same variant in MEN1 who had a giant pituitary adenoma and intracranial hypertension, similar to individual III.2 (family 4)." (PMID 36967793, 2023). "In a large study of pediatric and adolescent patients with pituitary adenomas screened for predisposing germline mutations, two adolescents with recurrent or difficult-to-treat CD were found to harbor germline MEN1 mutations among 74 subjects with CD." (PMID 37409236, 2023). "This patient harbored a mutation of the MEN1 gene c.1268G>A and presented with pituitary adenoma as well as parathyroid." (PMID 37929040, 2023). "Another factor determining the size at initial detection of CD-associated pituitary adenomas is the extent and frequency of tumor surveillance in patients known to have, or to be at risk for, MEN1." (PMID 37409236, 2023). "Less than 5% of all PitNETs arise from germline mutations as a part of syndromic diseases (i.e., MEN1 gene mutation in multiple endocrine neoplasia-1 (MEN1)) or as a familial isolated pituitary adenoma)." (PMID 36612109, 2022). "Although less than 3% of pituitary adenomas are associated with MEN1, they are present in 30–40% patients with this syndrome with prolactinoma being the most common subtype." (PMID 31847209, 2019). "There is a consensus that MEN1 should always be suspected in patients with ZES and another feature of MEN1 (hyperparathyroidism, pituitary adenoma, adrenal adenoma) or a family history of an MEN1 associated disease." (PMID 28965289, 2017). "Various MEN1 mutations have been implicated in pituitary adenoma, and pituitary adenomas with HRAS mutations show increased aggressiveness." (PMID 27175596, 2016). "Mutations in the genes known to cause pheo/PGL can rarely be associated with pituitary adenomas, whereas mutation in a gene predisposing to pituitary adenomas (MEN1) can be associated with pheo/PGL." (PMID 25494863, 2015). "Tumor tissue analysis identified LOH at the SDHB locus in three pituitary adenomas and loss of heterozygosity at the MEN1 locus in two pheochromocytomas." (PMID 25494863, 2015). "GH-producing tumors causing acromegaly occur in 3–6% of MEN1 patients, and an increased female-to-male ratio in MEN1 patients with pituitary adenoma and acromegaly is observed in familiar and sporadic cases." (PMID 25663877, 2015). "MEN1 is caused by germline mutations of themenin gene, which most frequently leads to the development of primary hyperparathyroidism, pituitary adenomas and pancreatic tumors." (PMID 25210615, 2014). "Additionally, PPGL can sometimes be linked to pituitary adenomas through mutations in specific genes, including those associated with MEN1." (PMID 39194755, 2024).
pituitary adenomas (continued). "Concurrent deletions involving these genes may contribute to predisposition to MEN1 and pituitary adenoma, as has been already postulated for the pathogenesis of the brown fat tumor hibernoma." (PMID 39336996, 2024). "Second, we did not look for mutations in other genes that may be associated with syndromic forms of pituitary adenomas, such as the multiple endocrine neoplasia type 1 (MEN1) gene." (PMID 37149543, 2023). "However, it is worth adding that if the MEN1 mutation is diagnosed and a pituitary adenoma occurs, only 5–25% of patients will develop acromegaly symptoms." (PMID 37373574, 2023). "In a large clinical and molecular analysis of 235 younger patients with apparently sporadic pituitary adenomas, two patients who presented with CD in their 20s were identified with the same germline variant of unknown significance in the MEN1 gene." (PMID 37409236, 2023). "For example, in a Men1 knockout mouse model, loss of cell-cycle control and pituitary tumourigenesis were associated with miR-15a, miR-16-1 and let-7a downregulation and cyclin D1 upregulation in pituitary adenomas compared to normal WT pituitaries." (PMID 35900839, 2022). "Thirty-three patients showed at least one other pathological feature related to MEN1, being the association of hyperparathyroidism and pituitary adenoma in the majority of cases (n = 17), followed by the hyperparathyroidism alone (15 cases) and pituitary adenoma (1 case)." (PMID 34681263, 2021). "Typically, MEN1 associated pituitary adenomas are benign, but may cause significant morbidity in the setting of hormonal hypersecretion, enlargement that impinges on the optic chiasm, pituitary apoplexy, or post-surgical hypopituitarism." (PMID 33716975, 2021). "In the whole MEN1-positive cohort, the rate of mutations in exon 2 was significantly higher (P = 0.03) in patients with pituitary adenomas than in those with other MEN1-related tumors, whereas the rate of mutations in exon 9 was significantly lower (P = 0.02) in patients without pituitary tumors." (PMID 29036195, 2017). "Pituitary adenomas associated with MEN1 differ from sporadic ones." (PMID 26124750, 2015). "Thus, the use of knockout mice has validated the putative oncogenic role of genes linked to familial pituitary adenomas such as MEN1 and AIP." (PMID 25136513, 2014). "Interestingly, the 11q13 locus also contains the Multiple Endocrine Neoplasia type 1 gene (MEN1; MIM♯ 131100), 2.4 megabases upstream from the AIP gene, which can cause familial pituitary adenomas; however, the phenotype of MEN1 and FIPA is different." (PMID 20506337, 2010). "While pituitary adenomas are frequently observed in MEN1 patients, the presence of additional tumors within the pituitary gland is unusual." (PMID 41155355, 2025). "Examination of the parathyroid and pituitary glands revealed concurrent hyperparathyroidism and a pituitary adenoma, confirming the diagnosis of MEN1, including a NET in the duodenum." (PMID 40487566, 2025). "Patients with MEN1 have a high risk for primary hyperparathyroidism (PHPT) with a penetrance of nearly 100%, pituitary adenomas (PitAd) in 40% of patients, and neuroendocrine neoplasms (NEN) of the pancreas (40% of patients), duodenum, lung, and thymus." (PMID 39826015, 2025). "The mostcommon is MEN1, an autosomal dominant disorder resulting from germline pathogenicvariants in the MEN1 gene, characterized by involvement of multiple parathyroidglands, pituitary adenomas, and pancreatic tumors." (PMID 40893023, 2025). "Another patient, initially diagnosed with a pituitary adenoma and later found to have a carcinoid tumor, underwent targeted genetic analysis for multiple endocrine neoplasia type 1 (MEN1)." (PMID 40868080, 2025). "In a multicenter retrospective study, including 324 patients with MEN1 that were compared with 110 patients with sporadic PitAd, 42% had pituitary adenomas, with a mean age at diagnosis of 38.0 years (range 12–83)." (PMID 39826015, 2025).
pituitary adenomas (continued). "In this case report, we describe a case of a female patient with MEN1 who experienced several recurrences of pituitary adenoma, ultimately necessitating surgical resection." (PMID 41155355, 2025). "In MEN1 patients, pituitary adenoma is a common pathology occurring in approximately 30–40% of the cases." (PMID 41155355, 2025). "Characteristics of MEN1-related pituitary adenomas in the entire population and according to secretory profile." (PMID 39439563, 2024). "Previous work highlighted MEN1 as a downstream TGFβ signaling component that regulates the growth and proliferation of pituitary adenoma cells and osteoblasts." (PMID 38891107, 2024). "Pituitary adenomas are the third-most common tumors in adults with MEN1 (30 to 50% of individuals), and the second-most common in children (34%), occurring at 5 years old." (PMID 39336996, 2024). "Some studies have shown that plurihormonal adenomas are more frequent in the context of MEN1 when compared to sporadic pituitary adenomas." (PMID 36967793, 2023). "The typical manifestations of MEN1 are (a) parathyroid hyperplasia/adenomatosis (>95%), (b) duodenal-pancreatic NETs (about 80%), and (c) pituitary adenoma (about 30–50%)." (PMID 37761922, 2023). "MEN1 is caused by inactivating germline variants of the MEN1 tumour suppressor gene that produce PHPT, gastro-entero-pancreatic neuroendocrine tumours, pituitary adenomas, and other tumours, such as bronchial/thymic carcinoids or lipomas." (PMID 37810884, 2023). "From this cohort, we have identified 34 families: only four with a phenotype of MEN1 and the other 30 families with the phenotype of familial isolated pituitary adenoma (FIPA)." (PMID 36967793, 2023). "Sporadic MEN1 (n = 55): All patients had PHPT, alone or in association with other main MEN1-related tumors, 71% had pituitary adenoma, 45% had GEP tumors, and 38% had adrenal lesions." (PMID 37484956, 2023). "describe an MEN1 patient with CS and two pituitary adenomas, one a corticotrope microadenoma, as well as ectopic production of corticotropin-releasing hormone from a thymic NET." (PMID 37409236, 2023). "In the Diagnosis cluster, the most studied topics are Hereditary Cancer Syndrome, Genetic Diagnosis and Family Screening, Pituitary Adenomas, and Development of MEN1." (PMID 35463033, 2022). "In their first study of 57 PAM patients, tumors from PAM patients, compared with “sporadic” pituitary adenomas or meningiomas, had lower MEN1 expression and, in turn, hyperactivation of the mTOR signaling pathway." (PMID 36325452, 2022). "The penetrance of pituitary adenoma in MEN1 is ~40% with lactotroph adenoma occurring most frequently (20%), and somatotroph, gonadotroph, and clinically nonfunctioning adenoma occurring infrequently (~5% each)." (PMID 35323929, 2022). "During the follow-up, MEN1 was associated with PHPT in every patient, PNET was present in three patients (50%), pituitary adenoma in two patients (20%), and adrenal tumor in three patients (50%)." (PMID 35696052, 2022). "A history of pituitary adenomas, pNETs, bronchial carcinoid, or duodenal endocrine tumors in the patient or first-degree relatives favor MEN1." (PMID 33716975, 2021). "Pituitary adenomas in MEN1 can be aggressive and invade surrounding structures including the skull base." (PMID 34993034, 2021). "Prolactinomas are the most prevalent pituitary adenomas in the context of MEN1 (65%), followed by somatotropinomas, ACTH-secreting tumors, and non-functioning tumors, the frequency of which is often overlooked." (PMID 33312161, 2020). "Clinical manifestations of pituitary adenomas in patients with MEN1 parallel those of sporadic tumors, hence they depend on hormone hypersecretion, tumor size, pathological features, and pituitary reserve." (PMID 33312161, 2020).
pituitary adenomas (continued). "Compared with SPAs and SMs, the protein p-AKT (phosphorylated at Ser473), p-mTOR (phosphorylated at Ser2448) all showed increasing expression trend, and MEN1 showed reducing expression trend in pituitary adenoma and meningioma samples of PAM." (PMID 31665029, 2019). "Clinical features of MEN1 include primary hyperparathyroidism, pituitary adenomas, and pancreatic neuroendocrine tumours." (PMID 31847209, 2019). "Alterations in miRNA expression, including downregulation of three putative ‘tumour suppressor’ miRNAs, miR-15a, miR-16-1 and let-7a, have been reported in several tumour types including non-MEN1 pituitary adenomas." (PMID 30389902, 2018). "Pituitary adenomas have rarely been described in patients with pheochromocytomas/paragangliomas, but have been frequently observed in patients with MEN1." (PMID 30456751, 2018). "The majority of pituitary adenomas in MEN1 patients are prolactinomas, followed by somatotrophinomas, corticotrophinomas and non-functioning adenomas." (PMID 26320859, 2016). "Known pheo/PGL genes (SDHA-D, SDHAF2, RET, VHL, TMEM127, MAX, FH) and pituitary adenoma genes (MEN1, AIP, CDKN1B) were sequenced using next generation or Sanger sequencing." (PMID 25494863, 2015). "The incidence of pituitary adenomas in MEN1 patients varies between 10 and 60%, while their symptoms depend on the type and the amount of the pituitary hormone secretion and/or the compression effects due to the size of the tumour." (PMID 21266030, 2011). "Inactivation of multiple endocrine neoplasia type 1 gene (MEN1) results in the development of multiple endocrine tumors, including pituitary adenomas, in mice and humans." (PMID 19356251, 2009). "Pituitary adenomas are more prevalent in women with MEN1 than in men (46.5% vs. 30.3%, respectively, p < 0.001), explained mainly by a higher rate of prolactinomas (25.5% vs. 15.2%, p = 0.001), and are also more often the presenting manifestation in women than in men (30.4% vs. 17.7%, p < 0.001)." (PMID 39826015, 2025). "The MEN1-Tasman variant is associated with increased risk for both non-functioning pituitary adenomas and prolactinomas." (PMID 39826015, 2025). "Furthermore, it expands the understanding of potential tumor associations within MEN1, providing insight for pathologists and clinicians into the rare possibility of concurrent tumors in addition to pituitary adenoma in MEN1 patients." (PMID 41155355, 2025). "When MEN1 involves the pituitary gland, pituitary adenomas develop." (PMID 40144450, 2025). "Pituitary adenomas are the first clinical manifestation in 13% of patients with MEN1." (PMID 39826015, 2025). "Characteristics of MEN1-related pituitary adenomas according to pituitary adenoma size." (PMID 39439563, 2024). "Up to 80% of MEN1 patients develop primary hyperparathyroidism associated with parathyroid adenomas and with a female predominance, while up to 25% develop pituitary adenomas (prolactinomas, growth hormone, rare TSH, ACTH, nonfunctioning)." (PMID 37239385, 2023). "In MEN1, like in sporadic tumors, prolactinomas are the most frequent pituitary adenoma seen." (PMID 37711900, 2023). "With the other control group, we defined a population in which none of the known genetic causes of pituitary adenomas, including MEN1 and AIPvar was present." (PMID 37711900, 2023). "MEN1 is known for three main characteristics (neuroendocrine tumors, parathyroid and pituitary adenomas, pheochromocytomas), which may also include skin alterations as well as thyroid disorders." (PMID 37239385, 2023). "ZES may be a manifestation of MEN1 together with a parathyroid adenoma (90%) and pituitary adenoma (30%–40%)." (PMID 37008936, 2023). "Interestingly, the two MEN2A cases were initially mistaken for MEN1, given the presence of pituitary adenoma and hyperparathyroidism, suggesting caution in interpreting a negative MEN1 genetic testing in such a scenario." (PMID 35743266, 2022).